CAV3 (caveolin 3)
Diseases named in the same sentence as CAV3 in open-access papers (continued):
Sharing a sentence is not in itself a finding about the gene and the disease.
cardiac hypertrophy (continued). "During cardiac hypertrophy and failure, Cav‐3 expression decreases, t‐tubule structure is disrupted and excitation–contraction coupling (ECC) is impaired." (PMID 30786093, 2019). "Previous work demonstrates that Cav-3 overexpression in cardiomyocytes is essential for promoting the protective signaling in pathological cardiac hypertrophy." (PMID 28420984, 2017). "A Cavin4/Cav3 complex co-localizes with α1-adrenergic receptors (α1-AR) in cardiomyocytes and α1-AR-induced cardiac hypertrophy is attenuated in Cavin4/Murc mutant mice." (PMID 27294373, 2016). "Caveolae are required for normal cardiac function: caveolin 3 (Cav3) is the muscle-specific caveolin isoform and Cav3 knockout mice develop hypertrophy and cardiomyopathy." (PMID 25211146, 2014). "Other studies indicate that cardiac hypertrophy results in decreased expression of cav-3 and that right heart left heart hypertrophy is enhanced in caveolin-1 KO and caveolin-1/3 double KO mice." (PMID 20436850, 2009). "It has also demonstrated that p42/44MAPK (ERK1/2) is hyperactivated in heart derived from caveolin-3 knockout mice, which can lead to cardiac hypertrophy." (PMID 20436850, 2009). "Caveolin-3 (Cav-3), a component of caveolae, is expressed in cardiac, skeletal, and smooth muscles and interacts with angiotensin II type 1 receptor that plays an important role in cardiac hypertrophy." (PMID 41144497, 2025). "Another study showed that transgenic mice with cardiac myocyte-specific overexpression of Cav3 that were subjected to transverse aortic constriction had increased survival, reduced cardiac hypertrophy, and maintenance of cardiac function compared with control mice." (PMID 33679876, 2021). "In support of this idea, Cav‐3 KO results in a progressive cardiomyopathy characterized by ventricular hypertrophy and dilatation and reduced fractional shortening, while a loss‐of‐function mutation in Cav‐3, T63S, has been associated with inherited hypertrophic cardiomyopathy." (PMID 30786093, 2019). "Indeed, global genetic knockout (KO) of Cav-3 results in a progressive cardiomyopathy characterized by ventricular hypertrophy and dilation as well as reduced fractional shortening." (PMID 30028203, 2018). "Cav-3 has been identified as a muscle-specific form of the caveolin family and plays a significant role in the pathophysiology of the heart, such as, cardiac arrhythmias, myocardial ischemia/reperfusion injury, cardiac hypertrophy, and heart failure." (PMID 28420984, 2017). "Additionally, Cav-3 overexpression attenuates cardiac hypertrophy and induces endogenous cardiac protection from myocardial I/R injury." (PMID 27733157, 2016). "Furthermore, some factors such as Cav-3 protect against cardiac hypertrophy and ischemia by increasing p-AKT signaling and ANP, partially due to mimicking ischemia-induced preconditioning." (PMID 27213000, 2016). "Caveolin-3 null mice also develop cardiac hypertrophy that leads to dilated cardiomyopathy." (PMID 23585895, 2013). "Thus, Cav-3 KO was associated with ventricular dilation but not cardiac hypertrophy or overt failure at 12 wk of age." (PMID 30028203, 2018). "Moreover, regulation of Cav-3 via adenovirus in myocytes was also recently successfully used to increase Cav-3 levels and regulate atrial natriuretic peptides, which are known to be key mediators of cardiac hypertrophy." (PMID 22934034, 2012). "Given the potential for Cav-3 to modulate cardiac hypertrophy, we next tested whether targeting Cav-3 specifically to cardiac myocytes in vivo would alter natriuretic peptide and Akt signaling and attenuate the development of cardiac hypertrophy induced by hemodynamic overload." (PMID 23060817, 2012). "We developed a cardiac-targeted (α-myosin heavy chain promoter) Cav-3 overexpression system that caused a greater than twofold increase in Cav-3 specifically in cardiac myocytes and subjected the mice to transverse aortic constriction (TAC) for 1 month, to induce cardiac hypertrophy." (PMID 23060817, 2012).
cardiac hypertrophy (continued). "Since Cav3 has been shown to regulate the activity of ERK and Akt in the heart and cardiac hypertrophy, we examined the phosphorylation of MAPKs and Akt in the heart of 16-week-old PTRF−/− mice." (PMID 27612189, 2016). "Dysregulated Ca2+-flux through LCC is thought to play a role in the development of cardiac hypertrophy, and early evidence suggests flux through LCC in Cav-3 rich microdoamins as a locus for this pathologic growth via the calcineurin-nuclear factor of activated T-cell signaling cascade." (PMID 23060817, 2012). "Although not directly targeted at Cav-3, LA419, a novel NO donor, was able to prevent cardiac hypertrophy caused by pressure overload in rats by successfully increasing endogenous NO levels." (PMID 22934034, 2012). "Cav1 Cav3 double knockout animals, which completely lack caveolins because CAV2 is degraded in the absence of CAV1, develop cardiac hypertrophy and contractile failure." (PMID 31782728, 2019).
cardiomyopathy (25 papers, 2012 to 2025). A disease of the heart muscle or myocardium proper. "The mice with deficient in both Cav-1 and Cav-3 develop more severe cardiomyopathy compared to the mice with deficient in either Cav-1 or Cav-3." (PMID 40041164, 2025). "We identified an indirect relation between gene CAV3 and hypoplastic left heart syndrome due to its strong association with cardiomyopathies and isolated cardiac defects." (PMID 39841745, 2025). "Nevertheless, the risk of cardiomyopathy linked to CAV3 mutations remains poorly studied, and this assumes clinical relevance when considering improvement in the muscular therapy of young patients with caveolinopathies." (PMID 38256054, 2024). "Mutations in the gene encoding caveolin-3 cause a broad spectrum of clinical phenotypes, ranging from persistent elevations in the serum levels of creatine kinase in asymptomatic humans to cardiomyopathy." (PMID 35329921, 2022). "The muscle-specific Cav-3 is essential for caveolae formation in cardiomyocytes, and Cav-3-deficient mice develop cardiomyopathies." (PMID 28877488, 2017). "On the contrary, loss of Cav-3 expression is prone to induce a molecular program leading to cardiomyocytes hypertrophy and cardiomyopathy." (PMID 28420984, 2017). "We show that haploinsufficiency for CAV3 increases susceptibility to palmitate‐induced global insulin resistance and causes cardiomyopathy." (PMID 27033451, 2016). "In mouse, mutations in Cav3 result in cardiomyopathy characterized by myocyte hypertrophy, dilation of the heart chambers, and a reduction in fractional shortening." (PMID 27294373, 2016). "Here we present a new mechanism for lipid-induced cardiac contractile dysfunction that resembles the cardiomyopathy observed in caveolin-3 loss-of-function mice." (PMID 23585895, 2013). "This view is further supported by the significant loss of caveolin-3 in heart samples of obese humans, which can be observed prior to other morphological changes that are associated with cardiomyopathy and heart failure." (PMID 23585895, 2013). "Depletion of caveolin-3 could contribute to loss of dyadic integrity, and junctophilin/caveolin-3 interactions are known to be suppressed in cardiomyopathy." (PMID 29202762, 2017). "Importantly, these mechanisms could also contribute to biogenesis of T-tubules in the heart as Cav3, cavin 1 and cavin 4 mutations lead to cardiomyopathies." (PMID 37083699, 2023). "Mice lacking Cav1 present a lipodystrophic phenotype, PAH, and cardiac disease, whereas Cav3 knockout mice, as expected from the muscle expression of Cav3, present cardiomyopathies and muscle disorders." (PMID 36980283, 2023). "Caveolin-1/caveolin-3-double knockout mice develop severe cardiomyopathy, compared to that in caveolin-1-knockout, caveolin-3-knockout, or wild-type mice." (PMID 32257548, 2020). "Cav3 knockout mice also show a cardiomyopathy characterized by hypertrophy, heart dilation and reduced contractibility." (PMID 31782728, 2019). "Cav3-null (Cav3−/−) mice show progressive cardiomyopathy, myopathic changes of the skeletal muscle, and impaired glucose tolerance and insulin resistance." (PMID 27612189, 2016). "Our study shows that palmitate-induced loss of caveolin-3 is associated with a contractile dysfunction phenotype that is similar to the cardiomyopathy reported in the caveolin-3 null mice." (PMID 23585895, 2013). "Global overexpression of Cav-3 was subsequently shown to result in severe cardiomyopathy and muscular dystrophy accompanied by downregulation of NOS." (PMID 23060817, 2012). "In addition to LMNA, mutations to CAV3, ACTA1, ACTC1, DYSF, and DSG2 are linked to cardiomyopathies and encode proteins that are long-lived in the heart." (PMID 37162946, 2023). "However, CAV3 knockout mice developed progressive cardiomyopathy and an incorrect DGC complex location." (PMID 33927797, 2021).
cardiomyopathy (continued). "Cav3−/− mice also develop cardiomyopathy with ERK activation in the heart, and Cav1 and Cav3 double-knockout mice exhibit a severe cardiomyopathic phenotype compared with Cav1−/− mice and Cav3−/− mice." (PMID 27612189, 2016). "Also there is a clear distinction between cases with non-obese cardiomyopathy and obese cardiomyopathy in the amount of caveolin-3 present in the T-tubule system (white arrows)." (PMID 23585895, 2013).
heart failure (25 papers, 2012 to 2025). Inability of the heart to pump blood at an adequate rate to meet tissue metabolic requirements. "In patients with heart failure, reduced levels of Cav-3 are associated with impaired calcium signaling and contractile dysfunction, underscoring its critical role in maintaining myocardial function." (PMID 40358155, 2025). "Given its essential functions in ion channel compartmentalization and T-tubule stabilization, Cav-3 deficiency leads to electrical instability and contractile impairment, further contributing to heart failure pathogenesis." (PMID 40358155, 2025). "Beyond more rare CAV3 mutations, Cav3 is also down regulated in the ventricle of animal models of heart failure and in human heart failure." (PMID 30473666, 2018). "We are currently investigating if decreased IK1 and INa in heart failure is related to loss of caveolae or Cav3 regulation." (PMID 30473666, 2018). "Additionally, reduced Cav-3 level in the heart has been shown to increase myocyte dis-contractility and the progression of heart failure through enhanced susceptibility to ventricular arrhythmia or β2AR signaling." (PMID 40041164, 2025). "The role of Cav-3 in the loss of t-tubular localization of β2-adrenoceptor signaling in heart failure might be tested in future studies by investigating the effect of C3SD peptide on the response of CAL myocytes to β2 stimulation." (PMID 29101175, 2018). "NEW & NOTEWORTHY Caveolin-3 (Cav-3) is a protein that inhibits hypertrophic pathways, has been implicated in the formation and function of cardiac t-tubules, and shows decreased expression in heart failure." (PMID 30028203, 2018). "In heart failure models, Cav-3 expression is significantly reduced, which correlates with deteriorating left ventricular function and T-tubule disorganization." (PMID 40358155, 2025). "Heart failure with reduced ejection fraction patients had the highest trans-coronary gradients of Con43 + TnT and Con43 + Cav3 EVs." (PMID 36330003, 2022). "sGC was found to redistribute away from caveolin-3 in heart failure, as demonstrated in this work by immunocytochemical double staining." (PMID 32228862, 2020). "Collectively, the cardiac-specific overexpression of caveolin-1 or caveolin-3 is a novel strategy to attenuate cardiac hypertrophy and heart failure." (PMID 32257548, 2020). "Further, the dominant-negative disruption of caveolin-3 function leads to far-reaching β2AR-cAMP signals similar to those observed in heart failure." (PMID 32257548, 2020). "Heart failure leads to altered co-localization of sGC and caveolin-3, as shown via immunocytochemical staining." (PMID 32228862, 2020). "In heart failure, the regulation of L-type Ca2+ current by β2-adrenoceptors is redistributed to the surface membrane, and the constitutive regulation by caveolin-3 is lost." (PMID 29101175, 2018). "The colocalization by Cav-3 is lost in heart failure, and both β2-adrenoceptors and LTCCs are redistributed from the t-tubular to surface sarcolemma membranes." (PMID 29101175, 2018). "Studies have shown a wide variation in the expression levels of caveolins and specifically Cav-3 in different heart failure models, with studies showing Cav-3 expression being increased, decreased or unchanged." (PMID 28498861, 2017). "The results suggest a potential pathophysiological role for Cav3, integrins and membrane repair in daunorubicin-induced heart failure." (PMID 28498861, 2017). "In line with this, blocking Cav3 channels is able to reduce arrhythmic events and sudden cardiac death in a mouse heart failure model." (PMID 22808078, 2012). "Unlike myocardial ischemia and heart failure, severe sepsis significantly increased Cav-3 expression in the heart, which was associated with dysregulated L-type calcium channels." (PMID 40041164, 2025). "Thus Cav‐3 overexpression provides specific but limited protection following induction of heart failure, although other factors disrupt Ca2+ release." (PMID 30786093, 2019).
heart failure (continued). "We hypothesized that the redistribution of ICa after CAL is due to loss of Cav-3-dependent localization at the t-tubules, which may be secondary to the decreased expression of Cav-3 observed in heart failure." (PMID 29101175, 2018). "Due to the complexity we have observed of cell type (modeling experiments) and the differences in effects by CAV3 mutations on IK1 and INa, we anticipate that there may also be a complex effect in heart failure on Kir2.x and Nav1.5 remodeling." (PMID 30473666, 2018). "The role of Cav-3 in the redistribution in heart failure remains unclear, but the data are consistent with a shift in Cav-3 from cholesterol-rich to noncholesterol-rich membranes." (PMID 29101175, 2018). "In mice, heart failure has been shown to decrease Cav3 mRNA expression accompanying a concordant change in its protein expression, suggesting that decreased Cav3 mRNA in the PTRF−/− heart is, in part, a secondary change attributable to cardiac dysfunction in PTRF−/− mice." (PMID 27612189, 2016). "We showed increased myocyte caveolae number and increased expression of Cav-3, activated β1 integrins, and the membrane repair protein MG53 in daunorubicin-induced heart failure." (PMID 28498861, 2017). "Thus, the present study advances previous findings from our laboratory that Cav-3 plays a role in the regulation of ICa at the t-tubule by PKA and β2-adrenoceptors in normal myocytes and that ICa is redistributed from the t-tubules to the surface sarcolemma in CAL-induced heart failure." (PMID 29101175, 2018).
limb-girdle muscular dystrophy (15 papers, 2009 to 2024). Limb-girdle muscular dystrophy (LGMD) is a heterogeneous group of muscular dystrophies characterized by proximal weakness affecting the pelvic and shoulder girdles. "On the other hand, mutations in the caveolin-3 gene causing the loss of caveolin-3 expression are responsible for an autosomal dominant form of limb-girdle muscular dystrophy (LGMD)." (PMID 37327338, 2023). "Inhibiting the turnover of mutant proteins has been investigated as a possible therapeutic treatment for dominant negative mutations in caveolin-3 associated with limb-girdle muscular dystrophy." (PMID 37206923, 2023). "Heterozygous mutations in the CAV3 gene give rise to limb-girdle muscular dystrophy (LGMD) 1C characterized by severe deficiency of caveolin 3 protein in muscle fibers." (PMID 26226340, 2015). "Mutations to caveolin-3, the main scaffolding protein of caveolae in muscle, cause Limbe-Girdle muscular dystrophy." (PMID 24023653, 2013). "Moreover, intramuscular injection of p29 alleviated muscle atrophy and decreased the absolute force in caveolin 3-deficient limb-girdle muscular dystrophy 1C model mice." (PMID 26226340, 2015). "At least 30 inactivating mutations have been identified in the human gene coding for caveolin-3, that lead to the loss of caveolae in skeletal muscle with four major associated disease complexes: limb-girdle muscular dystrophy, rippling muscle disease, hyperCKemia, and distal myopathy." (PMID 23585895, 2013). "Caveolin-3 (CAV3) is the main caveolar protein in skeletal muscle and is a key factor in muscle cell fusion, and several mutations in the CAV3 gene cause heterogeneous neuromuscular diseases including caveolinopathies such as LGMD1 (limb girdle muscular dystrophy)." (PMID 23272181, 2012). "Limb-girdle muscular dystrophy (LGMD) is a progressive muscle weakness affecting the pelvic and shoulder girdles, primarily caused by mutations in proteins like myotilin, lamin, caveolin-3, calpain-3, dysferlin, γ-sarcoglycan, TCAP, TRIM32, FKRP, and titin." (PMID 39415830, 2024). "In humans, null mutations in caveolin-3 (CAV3), which is expressed primarily in striated muscle, give rise to limb girdle muscular dystrophy." (PMID 26244347, 2015). "For example, mutations in muscle specific genes such as the calcium sensing sarcolemma protein Dysferlin and the endocytosis required protein caveolin-3, which lead to different human limb girdle muscular dystrophies (LGMD2B and LGMD1C, respectively), are required for cellular wound healing." (PMID 36139352, 2022).